CD2 (CD2 molecule)
Diseases named in the same sentence as CD2 in open-access papers (continued):
Sharing a sentence is not in itself a finding about the gene and the disease.
Autoimmunity (9 papers, 2015 to 2022). The occurrence of an immune reaction against the organism's own cells or tissues. "Polymorphisms in an ERBS within this QTL modulate E2-driven Cd2 expression, leading to sex-specific differences in T cell autoimmunity." (PMID 34552089, 2021). "Our results in mice suggested a regulatory role for CD2 on T-cell-dependent autoimmunity, which is genetically determined in a sex-linked manner." (PMID 34552089, 2021). "The importance of Egr2 and 3 in controlling the development of autoimmunity was discovered in aged CD2-specific Egr2-deficient mice and in CD2-specific Egr2- and Egr3-deficient mice." (PMID 28487311, 2017). "Since we used a hypothesis-free approach, our findings strongly suggest E2-mediated regulation of CD2 as a key physiological mechanism contributing to sex differences in T cell responses and the susceptibility to autoimmunity." (PMID 34552089, 2021). "Thus, subtle, physiological changes in CD2 expression caused by natural polymorphisms likely modify the risk of T cell-dependent autoimmunity in humans." (PMID 34552089, 2021). "Reduced Cd2 expression protected mice from T-cell-dependent inflammation and autoimmunity by reducing the activation and proliferation of antigen-specific T cells." (PMID 34552089, 2021). "Here we positionally identify a polymorphic estrogen receptor binding site that regulates Cd2 expression, leading to female-specific differences in T cell-dependent mouse models of autoimmunity." (PMID 34552089, 2021). "The D3-31 mice used in this study exhibit discrete changes in Cd2 expression mediated by E2, thus enabling us to study the effect of Cd2 on T-cell-mediated autoimmunity in a physiological setting." (PMID 34552089, 2021). "Clinical trials in the discussed autoimmune conditions are needed to evaluate the efficacy of CD2-targeting therapies in these patient groups." (PMID 32582179, 2020). "We have also previously observed that Egr2−/− MP CD4 T cells in old CD2- Egr2−/− mice, which are also prone to develop autoimmunity, have increased homeostatic proliferation." (PMID 32709717, 2020). "A CD2 cell adhesion molecule was previously shown to be an essential costimulator of T cells, preventing exhaustion in an autoimmunity setting, where CD2-dependent costimulation was significantly correlated with a poor prognosis in patients with autoimmune conditions." (PMID 35205827, 2022). "Our findings also show that CD2 is a sex-sensitive regulator of T-cell-mediated autoimmunity." (PMID 34552089, 2021). "Women, who are generally more prone to autoimmunity, express higher levels of CD2 than men." (PMID 34552089, 2021). "Most studies on CD2 in autoimmunity have focused on the expression of this molecule on T cells." (PMID 33391260, 2020). "Whether these cells have high propensity for tissue migration and whether this is important for the development of autoimmunity in CD2-Egr2/3−/− mice remains to be investigated." (PMID 32709717, 2020). "It will be of interest to explore whether CD2 costimulation of CD16-driven responses influence the functional reprogramming of the cell during expansion in a fashion similar to that noted in the context of T cell exhaustion in autoimmunity and infection." (PMID 27117418, 2016). "These alleles are analogous to the protective allele in human multiple sclerosis, suggesting that higher levels of CD2/CD58 expression and function have a protective effect against autoimmunity." (PMID 26438525, 2015).
oral mucositis (9 papers, 2017 to 2025). Inflammation of the mucous membranes of any of the structures in the mouth. "Among these studies, four clinical trials reported a decrease in the severity of oral mucositis by using specific strains of bacteria, including Lactobacillus (L. casei and L. brevis CD2) and B. clausii UBBC07." (PMID 38249451, 2023). "brevis CD2 lozenges were ineffective in protecting head and neck cancer patients from radiation-induced oral mucositis." (PMID 37242437, 2023). "In the context of cancer treatment, L. brevis CD2 lozenges have been found to reduce the occurrence of oral mucositis in patients undergoing high-dose chemotherapy." (PMID 38249451, 2023). "However, recent research found that the effects of L. brevis CD2 were unable to confirm its beneficial impact for severe oral mucositis, though one possible explanation for these findings could be the premature closure of patient accrual." (PMID 33920572, 2021). "Taking into consideration the major limitation of this study of not reaching the established number of patients due to a lack of LB CD2 supplies, no benefit was observed in using LB CD2 in reducing the incidence of oral mucositis." (PMID 37373922, 2023).
rheumatoid arthritis (9 papers, 2015 to 2026). A chronic, systemic autoimmune disorder characterized by inflammation in the synovial membranes and articular surfaces. "CD4-ERα knockout (KO) female mouse model showed a mild autoimmune phenotype with increased autoantibody and follicular helper T cells (TFH) production, while polymorphisms in ER binding site affect rheumatoid arthritis by introducing a sex bias Cd2 expression to regulate T cell activation." (PMID 40406098, 2025). "They systematically examined 370 SNPs from 179 independent loci with P < 1 × 10− 3, and three gene regions in CD28, PRDM1 and CD2/CD58 were identified that were closely related to rheumatoid arthritis." (PMID 31842750, 2019). "In addition, alterations in CD2/CD58 signaling are associated with multiple sclerosis and rheumatoid arthritis." (PMID 37596785, 2024). "Here, for the first time, we employed PLA to visualize the interaction between CD2 and CD58 proteins that are present on two different cells, Jurkat cells and human fibroblast-like synoviocyte-rheumatoid arthritis (HFLS-RA) cells, respectively." (PMID 30227746, 2018). "Interestingly, the CD2 activation epitope CD2R has been reported to be upregulated on T cells in the synovial fluid of rheumatoid arthritis (RA) patients and in the peripheral blood of patients with juvenile RA, systemic lupus erythematosus, ankylosing spondylitis, and Lyme disease." (PMID 32582179, 2020).
systemic mastocytosis (8 papers, 2013 to 2025). Systemic mastocytosis (SM) comprises a heterogeneous group of rare acquired and chronic hematological malignancies that are related to an abnormal proliferation of mast cells in tissue, including bone marrow, with or without skin involvement. "Typically, in systemic mastocytosis, the neoplastic mast cells show a dual expression of CD2 and CD25." (PMID 38337573, 2024). "Neoplastic MCs expressing CD25 and/or CD2 were described in systemic mastocytosis especially in aggressive systemic mastocytosis (ASM) and mast cell leukemia (MCL)." (PMID 28725969, 2018). "It is characterized by elevated numbers of immature atypical mast cells (> 10% metachromatic blasts) without meeting the full criteria for systemic mastocytosis, notably lacking CD2/CD25 expression, D816V KIT mutation, and focal dense mast cell infiltrates." (PMID 40751871, 2025). "Markers of systemic mastocytosis, i.e., CD2 and CD25, are less helpful." (PMID 38337573, 2024). "Flow cytometric immunophenotyping confirmed the presence of aberrant mast cells in all patients with systemic mastocytosis, with CD25 being more frequently expressed than CD2, aligning with findings from recent literature." (PMID 40893810, 2025). "In addition, the presence of excessive mast cells in tissue biopsies is not uncommon in other types of HES, and if there is any doubt regarding the diagnosis of indolent systemic mastocytosis, specific immunostaining (CD2, CD25) for activated mast cells may be considered." (PMID 37122022, 2023). "These neoplastic mast cells aberrantly express CD2 and CD25, which are the best markers for the definitive diagnosis of systemic mastocytosis." (PMID 24141298, 2013). "In addition to parasitic infections and drug-induced eosinophilia, chronic inflammatory bowel disease, celiac disease and systemic mastocytosis should be considered (in the latter case, it is worth considering staining with CD117, CD2 and CD25 on gastrointestinal tissue biopsies)." (PMID 37122022, 2023). "Finally, in cases of mastocytosis that are typically associated with unfavorable outcomes (i.e. aggressive systemic mastocytosis and mast cell leukemia), the mast cells exhibit aberrant expression of CD25 and usually do not express CD2." (PMID 24141298, 2013). "In contrast, mast cells from well differentiated systemic mastocytosis cases show normal expression of activation markers, lack of both CD25 and CD2, a phenotype similar to that of mature resting mast cells and high expression of CD117 and FcRIe, as the main features." (PMID 24141298, 2013).
COVID-19 (7 papers, 2021 to 2025). A disease caused by infection with severe acute respiratory syndrome coronavirus 2. "HLA-A*24:02-positive PBMCs from COVID-19 mRNA vaccine recipients were cultured with T cell activators (CD3/CD28/CD2) and IL-2 for 10 days to expand T cell populations." (PMID 41280906, 2025). "•PPI-identified hub genes IL7R/CD2/GZMA/CD3D/FCER1A diagnose COVID-19 and diabetic nephropathy with AUC>0.80, linking immune activation to tissue damage." (PMID 41332907, 2025). "Here, for the first time, we identified that the changes in the association between some of the microRNAs and CD1a, CD2, and CD11b were the most apparent alterations among AML patients after infection with COVID-19." (PMID 38902412, 2024). "In this prospective study of critically ill COVID-19 patients, the lymphocyte expression levels of CD markers for the examined T cell subsets (CD2, CD4, CD8, CD158d, and CD25) and CD127 as well as CD19 were lower in COVID-19 patients than in HCs." (PMID 35625671, 2022). "Patients with COVID-19 showed lower expression levels of lymphocyte surface CD markers during the first week for all the examined T subsets (CD2, CD4, CD8, CD158d, and CD25) as well as CD127 and B-cell marker CD19 compared to HCs (p < 0.001 for all)." (PMID 35625671, 2022). "Herein, upregulated CD2 indicated an enhanced immune response, which may impact the pathophysiology of both COVID-19 and DN." (PMID 41332907, 2025). "Hence, our findings offer new insights into the molecular mechanisms underlying COVID-19 and sepsis-induced ARDS and suggest CD3, CD247, CD2, CD40LG MMP-9, LCN2, and RETN as the potential targets for neutrophils in developing novel therapies and diagnostic tools for these diseases." (PMID 37822934, 2023). "For COVID-19, the AUCs of IL7R, CD2, GZMA, CD3D, and FCER1A were 0.925, 0.934, 0.905, 0.950, and 0.998, respectively." (PMID 41332907, 2025). "In a parallel analysis, the datasets from GSE152418 revealed pronounced differences in the expression of IL7R, CD2, CD3D and FCER1A when comparing COVID-19 samples to control samples." (PMID 41332907, 2025). "Of these, six hub genes (CD247, CD2, CD40LG, KLRB1, LCN2, RETN) showed significant alterations across COVID-19, sepsis, and geriatric sepsis-induced ARDS." (PMID 37822934, 2023). "We also found an increased expression of CD63, ITGB2, CD37, CD2 and IL23R markers and the reduction in CXCR4, CD69, CD48, ICAM1 and S100A10 markers in COVID-19-derived NK-T cells compared to controls." (PMID 34944610, 2021). "Results revealed a negative correlation between neutrophils and CD247, CD2, and KLRB1, and a positive correlation with RETN in both COVID-19 and sepsis." (PMID 37822934, 2023). "CD247, CD2, CD40LG, and KLRB1 displayed a positive correlation with CD8+ T cells and CD4+ T cells in both COVID-19 and sepsis cases, while LCN2 and RETN showed a negative correlation." (PMID 37822934, 2023).
acute lymphoblastic leukemia (6 papers, 2014 to 2024). Leukemia with an acute onset, characterized by the presence of lymphoblasts in the bone marrow and the peripheral blood. "For verification of the presence of (V)SLSLCs, we analyzed the levels of CD34, CD45, and CD2 markers in two Acute Lymphoblastic Leukemia (ALL) sub-types: Raji and Jurkat." (PMID 38067224, 2023). "CD2 is expressed in about 90% adult peripheral T-cell lymphoma and about 70% in pediatric T-acute lymphoblastic leukemia/lymphoma (ALL/LBL) and PTCL, higher than CD7 (40-50%)." (PMID 38711850, 2024). "T-cell acute lymphoblastic leukemia (T-ALL) presented with massive organomegaly and bone marrow involvement at a median latency of 230 days and 100% penetrance similar to what has been described in independently constructed CD2-Lmo2 transgenics; the latency was increased with backcrosses to B6." (PMID 24465765, 2014).
eosinophilia (6 papers, 2020 to 2025). "The pharmacologically delivered rIL-18 to CD2-IL-5 mice transformed naïve eosinophils to pathogenic intraepithelial eosinophilia and degranulating extracellular eosinophilic granules." (PMID 37524769, 2023). "As both IL-4, and IL-5 mRNA levels are unaffected by CD2 deficiency, yet eosinophilia was greatly reduced in HDME-treated Cd2−/− mice, our observations highlight the importance of IL-13 as the central regulator of HDME-induced lung inflammation." (PMID 32477356, 2020). "Therefore, to establish that rIL-18 indeed transform in vivo IL-5 generated naïve eosinophils to pathogenic eosinophils; therefore, we used CD2-IL-5 mice that do not have intraepithelial eosinophilia and degranulated eosinophils." (PMID 37524769, 2023). "While IL-5 is produced by T cells in both lines, the level of eosinophilia differs between the two mouse lines, with CD3.IL-5tg mice having higher baseline circulating eosinophil levels than CD2.IL-5tg (40%–60% versus 20%–30%, respectively)." (PMID 41050650, 2025). "Bone marrow flow cytometry demonstrated eosinophilia and 3% atypical T-cells with an immunophenotype of CD3−, CD4+, CD2+, CD5+, CD7−, CD8−." (PMID 41488087, 2025).
glioma (6 papers, 2013 to 2023). A benign or malignant brain and spinal cord tumor that arises from glial cells (astrocytes, oligodendrocytes, ependymal cells). "In previous work we have shown that γδ T cell cultures cultured ex vivo using a combination of anti-CD2, OKT-3, and IL-2 are cytotoxic to high-grade gliomas in vitro and to human xenograft tumors in immunodeficient mice." (PMID 23950874, 2013).
Sepsis (6 papers, 2020 to 2024). Sepsis is defined as life-threatening organ dysfunction caused by a dysregulated host response to infection. "Another study also found that CD2 is separately identified as the downregulated crucial gene set in sepsis." (PMID 36199375, 2022). "It showed association with CD2, IL2RB, and IL7R in adult SIRS and KLRG1 and TGFBR3 in adult sepsis, among others." (PMID 32318053, 2020). "A study also found that CD2 is identified as the down regulated crucial gene set in sepsis." (PMID 39654893, 2024). "Study showed some hub genes (CD2, CD27, GZMA, KLRB1, and PRF1) have been screened out as sepsis biomarkers and all of them were down regulated genes in sepsis, which consistent with our findings." (PMID 39654893, 2024). "CD4, CD8A, CD28, CD2, CD3E as T cell surface active molecules play important roles in the immune response process; among them, the roles of CD4 and CD8 T lymphocytes in sepsis have been widely recognized." (PMID 39654893, 2024). "Our findings revealed significant decreases in CD4, CD3e, IL-7R, CD5, CD247, CD2, CD40LG, ITK, and KLRB1, and significant elevations in MMP9, LCN2, and RETN in sepsis-induced ARDS compared to controls." (PMID 37822934, 2023). "Drawing upon the insights gleaned from our murine sepsis-induced ARDS model and human subjects afflicted with sepsis-induced ARDS, we selected CD247, CD2, CD40LG, KLRB1, LCN2, and RETN as the foci of our subsequent investigation." (PMID 37822934, 2023). "In sepsis, monocytes were negatively correlated with CD247, CD2, and CD40LG, while positively correlated with LCN2 and RETN." (PMID 37822934, 2023). "Moreover, we found that CD3, CD247, CD2, and CD40LG were negatively correlated with KC, whereas MMP-9, LCN2, and RETN were positively correlated with KC, suggesting that these candidate hub genes may regulate geriatric sepsis-induced ARDS by modulating the recruitment of neutrophils to the lung." (PMID 37822934, 2023).
colon cancer (5 papers, 2016 to 2025). "Most ICGs showed low mutation levels in colon cancer cases, except CD2, VTCN1, and LAYN." (PMID 34912802, 2021). "CD2 was found to be safer on healthy mice, therefore, in vivo studies were conducted with CD2 polymer and nanoplex in colon cancer-induced mice." (PMID 36839637, 2023). "There was a significant accumulation of CXCR4-expressing MDSCs around colonic tumours (50- to 100-fold), along with increased expression of pro-tumorigenic cytokines IL-17A and IL-1β, in Tff2-null and wild-type mice compared with CD2–Tff2 mice." (PMID 26841680, 2016). "When considering the duplication time of 2D colon cancer cells in RTCA, the increase in 5FU/IL2/CD2 nanoplexes was the highest compared with the 5-FU solution, 5-FU+IL-2 solution and other nanoplexes." (PMID 36839637, 2023).
HCMV infection (5 papers, 2018 to 2024). "A compensatory role of CD2 in the process of NK cell adaptation to hCMV infection was suggested in that study." (PMID 38534374, 2024). "To investigate the immunomodulatory effects of treatment with Tα1 + PCDs in CD4+ and CD8+ T cells during HCMV infection, we evaluated the expression of CD2 and CD40L, as well as the production of TNFα, IFNγ and IL-2 using multiparametric cytometry." (PMID 38396631, 2024). "Furthermore, the essential role of CD2 expression in hCMV infection was demonstrated." (PMID 38534374, 2024). "FcεRIγ−NKG2C+ cells exhibited high CD2 expression, low NKG2A+ and CD161+ cell frequency, and low PLZF expression early after acute HCMV infection." (PMID 31867015, 2019). "Recently, CD2 and CD58 were found to be greatly upregulated on the adaptive NK cells and fibroblasts under HCMV infection." (PMID 29904386, 2018). "Upregulation of CD2 on NK cells may be a generic response to HCMV infection since the HCMV UL148 gene product reduces expression of CD58, which restricts co-stimulation through CD2 and reduces HCMV-specific T cell and NK cell activation." (PMID 30857329, 2019).
mastocytosis (5 papers, 2013 to 2022). A clonal myeloproliferative neoplasm characterized by the proliferation and accumulation of neoplastic mast cells in one or multiple organs or organ systems. "The negative staining for T-cell, B-cell, CD61, and CD42b helped exclude other hematopoietic malignancies, and negative results for mast cell tryptase, CD2, and CD25 excluded mastocytosis." (PMID 26351594, 2015). "Whereas the expression of CD25 and/or CD30 on skin MC has been shown to correlate with the presence of SM in adults, expression of CD2, CD25 and CD30 could not clearly be correlated with a certain subtype of paediatric mastocytosis or with its prognosis." (PMID 35596520, 2022).
acute myeloid leukemia (4 papers, 2018 to 2025). Acute myeloid leukemia (AML) is a group of neoplasms arising from precursor cells committed to the myeloid cell-line differentiation. "We evaluated the response of J76 PRAME TPR expressing CD2::CD28 receptors to primary acute myeloid leukemia (AML) cells that express no CD28 ligands CD80 and CD86." (PMID 29707134, 2018).